FBXO32 (F-box protein 32)
Diseases named in the same sentence as FBXO32 in open-access papers (continued):
Sharing a sentence is not in itself a finding about the gene and the disease.
cancer (127 papers, 2010 to 2026). A tumor composed of atypical neoplastic, often pleomorphic cells that invade other tissues. "As a potential downstream target gene for FOXK2, FBXO32 has been found to exhibit both cancer‐causing and anti‐cancer properties in different types of cancer." (PMID 39552461, 2024). "Importantly, skeletal muscle wasting followed the same pattern as total body weight and was associated with Fbxo32 up-regulation, adding more similarities between this model and the syndrome observed in cancer patients." (PMID 32708666, 2020). "During cancer cachexia, this pathway is specifically upregulated in skeletal muscle cells, through the expression of ubiquitin ligases such the Atrogin-1, encoded by the Fbxo32 gene." (PMID 32708666, 2020). "The Fbxo32 gene encodes the protein atrogin-1, which has already been demonstrated to be an E3 ubiquitin ligase that is upregulated in muscle atrophy and that may be a potential molecular target for treating muscle atrophy induced by cancer cachexia." (PMID 32708666, 2020). "F‐Box Protein 32 (FBXO32), a F‐box protein family member, exhibits oncogenic and tumor‐suppressive roles in various carcinomas." (PMID 41000374, 2025). "In future research, it is necessary to further investigate the functions of FOXK2 and FBXO32 in cancer cells and the tumor environment." (PMID 39552461, 2024). "Additional research is required to completely understand the mechanisms that are responsible for the participation of FOXK2 and its subsequent gene FBXO32 in cancer, as well as to explore the possible advantages of focusing on FOXK2 for cancer treatment." (PMID 39552461, 2024). "FBXO32, a member of the F-box protein family, is known to play both oncogenic and tumor-suppressive roles in different cancers." (PMID 38643215, 2024). "MuRF-1/Trim63 and Atrogin1/Fbxo32 are well-known E3 ligases that are upregulated in conditions that lead to muscle wasting, such as those seen in chemotherapy, cancer cachexia, glucocorticoid treatment, and muscle disuse." (PMID 38234397, 2023). "Results obtained for FBXO32, ZHX1 and ANXA13 genes encoded within the same region as ATAD2 clearly emphasize the specificity of ATAD2 and MYC as well as ATAD2 and cancer stemness associations." (PMID 35049055, 2022). "More recently, FBXO32 has been also involved in cancer development and several reports ascribed an anti-tumorigenic role to FBXO32." (PMID 33462405, 2021). "Although not all F-box proteins have good characteristics, many F-box proteins, such as SKP2, FBXW7, FBXO4, and FBXO32, are related to the cancer development and progression and cancer cachexia." (PMID 34950036, 2021). "Among the 52 deregulated genes identified in our analysis, six of the nine studies included in the meta-analysis have evaluated the expression of Trim63 and Fbxo32 as molecular markers of muscle atrophy in cancer cachexia." (PMID 31013615, 2019). "Since EMT plays a critical role in tumorigenicity and metastasis, we interrogated a large panel of human cancers for FBXO32 expression and revealed a very strong induction of FBXO32 in various tumor types compared to the matched normal tissues." (PMID 29142217, 2017). "These range of findings and validations, in several model systems and primary cells from human and mouse, establish a critical role of FBXO32 in promoting tumorigenicity and metastasis in cancers." (PMID 29142217, 2017). "FBXO32 is also highly amplified in a large panel of cancers, and its depletion severely impairs the metastatic properties of cancer cells both in vitro and in vivo." (PMID 29142217, 2017). "F‐Box Protein 32 (FBXO32), in particular, is crucial to malignant tumor progression." (PMID 41000374, 2025). "Additionally, although our study primarily focused on HCC, aberrant FBXO32 expression has been observed in various malignant tumors." (PMID 41000374, 2025). "FBXO32's role in cancer immune response was explored through analysis." (PMID 39552461, 2024).
cancer (continued). "In addition, transcriptome analysis of a large set of cancer cell lines confirmed an enhanced expression of FBXO32 in mesenchymal cancer cell lines as compared to epithelial counterparts." (PMID 29142217, 2017). "Consequently, pharmacological FBXO32 inhibition may improve tumor therapeutic responses in other cancer types, which warrants further investigation." (PMID 41000374, 2025). "Moreover, they showed the anti-cancer function of DZNep in inducing cell death in BC cells by re-expressing PRC2-repressed genes, such as FBXO32, LAMB3, PLAU, PPP1R15A, TGFBI, IGFBP3, and TNS3; furthermore, FBXO32 was associated with DZNep-induced apoptosis." (PMID 34595180, 2021). "FBXO32 may regulate cancer relevant processes through several targets." (PMID 32226545, 2020). "Moreover, the role of FBXO32 in EMT regulation is dependent on the cancer type." (PMID 30999935, 2019). "However, despite these advances and indications of its role in cancer, the function of FBXO32 in EMT progression, metastasis and its contributions to the gene regulatory circuitry underlying these processes remain completely unknown." (PMID 29142217, 2017). "For investigating FBXO32's part in HCC, we exploited RNA‐Seq data from Cancer Genome Atlas (TCGA) database to obtain FBXO32 expression profiles in normal and cancer tissues." (PMID 41000374, 2025). "The KEGG pathways indicated that FBXO32 was related to ECM–receptor interaction, PI3K-Akt signaling pathway, proteoglycans in cancer, and regulation of actin cytoskeleton." (PMID 35046938, 2021). "The E3 ubiquitin ligase, Atrogin-1 (MAFbx/FBXO32), is a major effector of increased muscle proteolysis in cancer cachexia." (PMID 33925786, 2021). "Several studies described the increased expression of the muscle RING-finger protein-1 (MuRF1) and Atrogin-1 (known as F-box protein 32, FBXO32) E3 ubiquitin ligases in atrophic muscles during cancer cachexia." (PMID 33803685, 2021). "Relative to IOSE80, all cancer cell lines exhibited upregulated expression levels of LINC00494 and NFκB1 as well as downregulated expression level of FBXO32." (PMID 33585183, 2020). "Altogether, our findings provide the first report on FBXO32 as a highly potent and new regulator of EMT in both development (e.g., neurogenesis) and disease (e.g., cancer metastasis) contexts of EMT." (PMID 29142217, 2017). "Here, the authors show that an E3 ubiquitin ligase, FBXO32, regulates EMT via CtBP1 and the transcriptional program, and also mediates cancer metastatic burden and neurogenesis." (PMID 29142217, 2017). "Six studies evaluated expression of both FBXO32 and TRIM63 in patients with cancer." (PMID 31498843, 2019).
tumor (103 papers, 2010 to 2025). "FBXO32 is a tumor-suppressor gene that encodes an F-box protein, constituting one of the four subunits of the ubiquitin protein ligase complex." (PMID 38542354, 2024). "IDH1 mutation in CT26 tumor-bearing mice resulted in increased expression of Ube2d1, Trim63, and Fbxo32, while ivosidenib treatment inhibited the upregulation of UPP-related enzymes." (PMID 37741882, 2023). "Hematoxylin and eosin (H&E) staining on these tumors showed a more compact organization of cells in FBXO32 depleted primary tumors as compared to the control tumors, which may be linked to the reduced metastatic behavior of FBXO32-depleted tumor cells." (PMID 29142217, 2017). "Results showed that KPC tumor-induced increase in the mRNA levels of Fbxo32, Trim63, Map1lc3b, Cd36, Acox3, and spliced-Xbp1 (sXbp1) in skeletal muscle were significantly reduced by treatment of mice with 4μ8C." (PMID 40655023, 2025). "In particular, the ubiquitination regulation of FBXO32 is involved in various tumors through both oncogenic and tumor‐suppressive functions." (PMID 41000374, 2025). "Studies have found that FBXO32 degrades c-Myc through ubiquitination, inhibiting its mediated glycolysis and glutamine metabolism, thereby reducing lactic acid accumulation in the tumor microenvironment and improving the functional failure of CD8 +T cells." (PMID 40534867, 2025). "Further analysis revealed that the FBXO32 promoter was hypomethylated in tumor tissues, as confirmed by bisulfite sequencing PCR (BSP)." (PMID 41000374, 2025). "Immunohistochemical (IHC) analysis revealed significantly higher FBXO32 staining scores in tumor tissues." (PMID 41000374, 2025). "Tumor size decreased in the FBXO32 knockdown group and increased in the FBXO32 overexpression group." (PMID 41000374, 2025). "To explore FBXO32's impact upon tumor growth in vivo, we created a mouse subcutaneous xenograft model." (PMID 41000374, 2025). "Consistent with the observations in the mouse model, targeting FBXO32 in the PDO model significantly inhibited tumor growth." (PMID 41000374, 2025). "At present, the role played by FBXO32 in tumorigenesis and progression is debated, and it has been shown that FBXO32 can act as either a tumor-promoting or a tumor-suppressing gene." (PMID 38643215, 2024). "We further corroborate our findings using in vivo mouse models of metastasis and confirmed that FBXO32 positively regulates LUAD tumor metastasis." (PMID 38643215, 2024). "On a molecular level, we observed significant decreases in Trim63, Fbxo32, and Perp in muscles of mice bearing T4 shPerp 145 and T4 shPerp 146 tumors compared with control T4 shScr tumor mice." (PMID 34874916, 2022). "The A549 tumour-induced expression of skeletal muscle atrophy-related genes, such as Mstn, Fbxo32, and Trim63 was mitigated upon treatment with 2% Pc-Ex." (PMID 35406121, 2022). "Consistent with in vitro observations, Trim63 (young, P = 0.0187; aged, P = 0.045) and Fbxo32 (young, P = 0.0491; aged, P = 0.0262) gene expression was increased in skeletal muscle lysates prepared from tumor-bearing mice." (PMID 34874916, 2022). "Further validating the results of the GEPIA database, FBXO32 was related to the tumor stage of PDAC patients." (PMID 35046938, 2021). "The methylation levels of FBXO1, FBXO20, FBXO32, and FBXO45 were associated with tumor differentiation." (PMID 35046938, 2021). "The WFA 4 mg/kg group exhibited a significant reduction in relative gene expression of Fbxo30, Fbxo32, Trim63, and Traf6 compared to the tumor-free vehicle-treated group (p < 0.0001, p = 0.04, p = 0.02, p < 0.0001, respectively)." (PMID 33718372, 2021). "Interestingly, genes encoding ubiquitin ligases (Trim63, Fbxo32/MAFBx, Fbxo31, and Fbxo30/Musa1) that target muscle proteins and serve as markers of muscle atrophy were found to be transcriptionally upregulated in the gastrocnemius muscles from the tumor‐bearing mice." (PMID 32730698, 2020).
tumor (continued). "To functionally assess the contribution of FBXO32 to the mesenchymal state in a disease context, we investigated FBXO32 expression in certain tumor cell lines that are routinely used for such studies." (PMID 29142217, 2017). "Notably, targeting FBXO32 significantly inhibited tumor growth in both an orthotopic HCC model and an organoid model derived from HCC patients." (PMID 41000374, 2025). "FBXO32 can indirectly or directly regulate the expression of immune checkpoint molecules such as PD-L1 through multiple signaling pathways, thereby promoting tumor immune escape." (PMID 40534867, 2025). "Targeting FBXO32 is a potential treatment strategy for inhibiting tumor progression in HCC." (PMID 41000374, 2025). "Further exploration of FBXO32‐targeting strategies may reduce tumor recurrence and improve survival outcomes in HCC patients." (PMID 41000374, 2025). "FBXO32 can regulate cell apoptosis and play a tumor suppressor role." (PMID 40534867, 2025). "This dynamic balance may explain the functional heterogeneity of FBXO32 among different tumor types." (PMID 40534867, 2025). "Adeno‐associated virus (AAV) type 8 vector‐mediated RNA interference targeting Fbxo32 (AAV‐shFbxo32) dramatically suppressed orthotopic tumor growth derived from luciferase‐tagged mouse HCC cell line Hepa1‐6 in C57BL/6 mice, as evidenced by the reduced luciferase bioluminescence intensity." (PMID 41000374, 2025). "Interestingly, we previously showed that FBXO32 is essential for conferring the microenvironment that drives tumor aggressiveness." (PMID 38480932, 2024). "Finally, it was found that FBXO32 was the gene with the strongest correlation and most significant difference with tumor OS." (PMID 39552461, 2024). "FBXO32 has been reported to play a vital role in tumor invasion and metastasis." (PMID 38643215, 2024). "FBXO32 is also expressed in the smooth muscle of vasculature, uterus, and tumor tissues." (PMID 37175415, 2023). "However, in this study, we found that FBXO32 expression was elevated with tumor progression in tissues of EOC patients." (PMID 31810245, 2019). "Emerging evidence has identified FBXO32 as a tumor suppressor because it induces apoptosis." (PMID 30999935, 2019). "In support of our observations, FBXO32 levels correlated positively with the levels of established mesenchymal markers and negatively with the levels of epithelial markers in different types of tumor examined." (PMID 29142217, 2017). "For example, in liver cancer, the high expression of FBXO32 may promote tumor proliferation by stabilizing the D-type cyclin (CyclinD), and at the same time improve metabolic inhibition by inhibiting c-Myc, suggesting that its dual effects need to be combined with specific microenvironment analysis." (PMID 40534867, 2025). "We also identified the downstream gene FBXO32 of FOXK2 and, for the first time, found through differential expression gene enrichment analysis that it may be related to cellular ribosome‐associated pathways, thereby affecting tumor cell ribosome." (PMID 39552461, 2024). "Although FOR did not recover body weight in the presence of DOX treatment or potentiate the tumor weight reduction, it was able to recover the grip strength and the muscle mass (p<0.05), in addition to reducing the gene expression of Trim63 (p < 0.01) and Fbxo32 (p < 0.05)." (PMID 38234397, 2023). "The EEF1A1 gene is known to interact with the FBXO32 gene to promote PDAC progression and contribute to tumor growth and metastasis." (PMID 39688793, 2025). "IHC analysis revealed a significant reduction in FBXO32 levels after AAV8‐shFbxo32 treatment, and Ki67 staining further demonstrated that targeting FBXO32 inhibited tumor growth." (PMID 41000374, 2025). "Lastly, the EHD2, CTIF, FBXO32, PIP5K1C, and AHNAK genes were found to be co-expressed in the adjacent healthy tissue and tumor tissue groups." (PMID 37365287, 2023).
tumor (continued). "To further validate the effect of RAI14 on tumor growth, we detected Ki67, RAI14, FBXO32 and c-MYC by using immunohistochemistry." (PMID 36233342, 2022). "To determine if aging affects molecular determinants of muscle wasting in our models, we measured the expression of the atrogenes Fbxo32, Trim63, Foxo3a, and Cathepsin-L in skeletal muscle of young and old LLC and C26 tumor cell injected mice." (PMID 35008253, 2021). "In the tumor-bearing animals, treatment with WFA led to a statistically significant dose-dependent transcriptional downregulation of Fbxo30, Fbxo32, Trim63, and Traf6 compared to the tumor-bearing vehicle-treated group (p < 0.0001 for all comparisons)." (PMID 33718372, 2021). "GSE62452 demonstrated that the higher expression levels of FBXO1, FBXO20, FBXO32, and FBXO45 were correlated with poorer tumor differentiation (N = 68), apart from FBXO22 and FBXO38." (PMID 35046938, 2021). "Furthermore, ivosidenib preserved skeletal muscle mass by decreasing the expression of the E3 ligases Trim63 and Fbxo32, as well as inhibiting the production of D2HG in tumor and serum." (PMID 37741882, 2023). "The data from GSE62165 showed that none of the six-FBXOs was associated with tumor location (N = 118), while GSE21501 displayed that FBXO28 and FBXO32 were tightly linked to tumor size (N = 98); FBXO32 was also related to lymphatic metastasis (N = 101)." (PMID 35046938, 2021). "FBXO32 (F-box protein 32) is a novel TGF-beta/SMAD4 target gene, which is recently recognized to be highly upregulated in human normal ovarian surface epithelium, where it functions as a tumor suppressor." (PMID 33585183, 2020). "In addition, besides KLF4, FBXO32 can target some other unidentified substrates that are important in EMT, cell migration/invasion, and tumor development to establish its dual functions." (PMID 33240028, 2020). "To further investigate the role of FBXO32 in primary tumor growth and metastasis formation, we generated MDA-MB-231 cells (containing GFP and a luciferase reporter) with stable integration of a control shRNA or validated shRNA against FBXO32." (PMID 29142217, 2017). "Moreover, FBXO32 expression showed the expected correlation with the levels of established EMT markers as well as the identified FBXO32-induced EMT genes in multiple cancers, corroborating its critical role during human tumor metastasis." (PMID 29142217, 2017). "Moreover, FBXO32 levels correlated positively with the levels of established mesenchymal markers and identified FBXO32-induced EMT genes, while it negatively correlated with the levels of epithelial markers in all studied tumor types." (PMID 29142217, 2017). "The primary tumor growth was severely reduced in the absence of FBXO32 over time." (PMID 29142217, 2017). "In addition, FBXO32-mediated epithelial-mesenchymal transformation (EMT) enhances the expression of Snail and ZEB1 through CtBP1 ubiquitination in breast cancer, which not only promotes tumor metastasis, but also upregulates PD-L1 and attracts MDSCs, further weakening the anti-tumor immune response." (PMID 40534867, 2025).
infection (10 papers, 2008 to 2025). The state of being infected such as from the introduction of a foreign agent such as serum, vaccine, antigenic substance or organism. "To investigate the effects of FBXO32 on the odontoblastic differentiation of hDPSCs, we established FBXO32-knockdown (KD) hDPSCs and FBXO32-overexpression (OE) hDPSCs via lentiviral infection." (PMID 37175415, 2023). "Elevated FBXO32 levels during infection may contribute to muscle atrophy, potentially serving as a mechanism for energy conservation." (PMID 40943072, 2025).
cardiac diseases (3 papers, 2016 to 2023). "Based on these predictions and because FBXO32 has been associated with cardiac diseases in loss and gain of function studies in mice, we considered the FBXO32 variant further for functional analyses." (PMID 26753747, 2016). "Besides Atrogin-1 (Fbxo32) and Fbxo25, published data about the role of the F-box proteins in cardiac diseases and growth control is still rare." (PMID 36969608, 2023).
cardiovascular disease (1 paper, 2022). "An F-box protein well-known for its involvement in cardiovascular disease is FBXO32 (or Atrogin-1), a protein specifically expressed in skeletal and cardiac muscles." (PMID 35327608, 2022).
FBXO32 also shares sentences with these, for which no sentence is quoted: Skeletal muscle atrophy (36 papers); Obesity (19); Insulin resistance (15); myopathy (11); chronic obstructive pulmonary disease (8); Hyperglycemia (7); dilated cardiomyopathy (6); renal failure (6); endotoxemia (5); amyotrophic lateral sclerosis (4); myocardial infarction (4); vitamin D deficiency (4); Arthritis (3); chronic heart failure (3); Lewis lung carcinoma (3); type 1 diabetes (3); age (2); bladder cancer (2); Cerebral ischemia (2); emphysema (2); familial hypertrophic cardiomyopathy (2); lung fibrosis (2); metabolic disorders (2); myasthenia (2); peripheral nerve injury (2); adenocarcinoma (1); AIDS (1); Cirrhosis (1); Cognitive impairment (1); Cognitively (1).
A further 49 diseases each share a sentence with FBXO32 in 1 paper.